MYB (MYB proto-oncogene, transcription factor)
Diseases named in the same sentence as MYB in open-access papers (continued):
Sharing a sentence is not in itself a finding about the gene and the disease.
cervical cancer (10 papers, 2017 to 2025). A primary or metastatic malignant neoplasm involving the cervix. "This study aimed to elucidate the role of MYB in regulating NK cell cytotoxicity and its underlying mechanism in cervical cancer cells." (PMID 40888643, 2025). "In summary, MYB inhibited NK cell cytotoxicity by activating the hedgehog signaling pathway in cervical cancer, suggesting its potential as a novel diagnostic marker and immunotherapeutic target." (PMID 40888643, 2025). "On these grounds, we speculated that MYB was implicated in NK cytotoxicity in cervical cancer." (PMID 40888643, 2025). "However, it is elusive whether MYB is implicated in NK cytotoxicity in cervical cancer." (PMID 40888643, 2025). "While the current literature primarily evidences this regulation in cervical cancer, our preliminary experimental data indeed reveal a targeting and negative regulatory relationship between miRNA-195-5p and MYB in TNBC cell lines." (PMID 41141380, 2025). "Data in this investigation supported that MYB was in high‐expression status and was able to repress the NK cell impact on killing cervical cancer cells." (PMID 40888643, 2025). "In this study, we generated a result that high MYB expression suppressed the NK cell impact on killing cervical cancer cells through cell experiments." (PMID 40888643, 2025). "The observations supported the view that MYB was in high‐expression status and activated the hedgehog signaling pathway to suppress the killing of NK cells on cervical cancer cells." (PMID 40888643, 2025). "MYB expression, as well as the impact of MYB on the role and mechanism of NK cytotoxicity in cervical cancer, was investigated." (PMID 40888643, 2025). "In conclusion, these findings evidenced, for the first time, that MYB repressed NK cytotoxicity in cervical cancer, and such repression was achieved by activating the hedgehog signaling pathway." (PMID 40888643, 2025). "MYB is a proto‐oncogene and is upregulated in cancers like cervical cancer, manipulating cancer progression." (PMID 40888643, 2025). "T‐test results revealed that MYB level was substantially higher in cervical cancer tissues than in normal tissues." (PMID 40888643, 2025). "In conclusion, our findings provide evidence in favor of MYB being a possible immunotherapeutic target for cervical cancer." (PMID 40888643, 2025). "Emerging evidence highlights that MYB drives oncogenic growth in multiple tumors, including cervical cancer." (PMID 40888643, 2025). "Given this knowledge gap, this study endeavored to delineate the influence of MYB on NK cytotoxicity and its mechanism in cervical cancer." (PMID 40888643, 2025). "Together, these findings revealed that high MYB expression inhibited the NK cell impact on killing cervical cancer cells." (PMID 40888643, 2025). "Functional experiments demonstrated that MYB overexpression activated the hedgehog signaling pathway, thereby suppressing NK cell cytotoxicity in cervical cancer." (PMID 40888643, 2025). "MYB was observed to restrain NK cell impact on killing cervical cancer cells through activation of the hedgehog signaling pathway." (PMID 40888643, 2025). "MYB levels in HUCEC, Caski, HeLa, and SiHa cells were assayed by qRT‐PCR, which revealed a marked high expression of MYB in cervical cancer cells." (PMID 40888643, 2025). "A PPIN of 90 genes identified FLT1, IGF2, IRS1, JUN, KDR, ZEB1, TIMP2 (downregulated), and EZH2, SOX2, and MYB (upregulated) in cervical cancer samples when compared with normal samples." (PMID 36879084, 2023). "Considering the findings, MYB may act as an immunotherapeutic target for NK cell‐based elimination of cervical cancer cells." (PMID 40888643, 2025). "MYB expression in cervical cancer tissues and cells was analyzed using bioinformatics and qRT‐PCR." (PMID 40888643, 2025). "However, a closer examination of the uncharacterized function and mechanism of MYB in cervical cancer is warranted." (PMID 40888643, 2025).
cervical cancer (continued). "Bioinformatics and qRT‐PCR analyses revealed MYB overexpression in cervical cancer." (PMID 40888643, 2025). "Future studies could also examine MYB expression in NK cells from cervical cancer patients to further validate our findings." (PMID 40888643, 2025). "Previous studies have shown that circCCDC134 enhanced its stability and promoted HIF1A transcription by m6A modification, thereby promoting cervical cancer growth and metastasis by serving as a recruitment p65 in the nucleus and a miR-503-5p sponge regulating MYB expression in the cytoplasm." (PMID 38778089, 2024). "Moreover, circCCDC134 showed a dual tumor-promoting mechanism in cervical cancer by either recruiting p65 in nucleus or serving as a miR-503-5p sponge to regulate the expression of MYB in cytoplasm, ultimately enhancing HIF1A transcription." (PMID 37495592, 2023). "Thus, MYB was nominated as a possible immunotherapeutic target for cervical cancer, and suppression of MYB may be an alternative way to activate NK cell‐mediated elimination of tumor cells." (PMID 40888643, 2025). "On the other hand, miR-195 is shown down-regulated in cervical cancer and its overexpression inhibits proliferation, G1-S transition, migration and invasion through Cyclin D1, Cyclin D2, MYB proto-oncogene, transcription factor (MYB) and Smad 3 down-regulation via 3′UTR." (PMID 28216603, 2017). "We found a study that reported overexpression of miR-195 inhibits cervical cancer progression by targeting CCND1 and MYB." (PMID 39095857, 2024). "Previously, no study reported the specific mechanism behind MYB affecting NK cell killing in cervical cancer, and thus, this result contributed to the understanding of the molecular mechanism and provided avenues for identifying therapeutic targets in cervical cancer." (PMID 40888643, 2025). "Furthermore, to determine whether si‐MYB or oe‐MYB affects the expression of the HPV E7 oncoprotein, we examined HPV E7 levels in MYB‐knockdown or MYB‐overexpressing SiHa and HeLa cells (cervical cancer cell lines harboring integrated HPV16 and HPV18 DNA, respectively)." (PMID 40888643, 2025).
salivary gland tumors (9 papers, 2014 to 2025). "In salivary gland tumors, about one-third to two-thirds of cases depicted MYB gene alteration, which is represented in breast AdCC approximately 38–100% of the time." (PMID 35590093, 2022). "In addition, previous studies have shown that MYB protein can be expressed not only in AdCC, but also in other salivary gland tumors." (PMID 35590093, 2022). "The problem of histological overlap between different salivary gland tumors may be exemplified by a report which identified an instance of MYB-NFIB fusion in a tumor diagnosed as PLGA." (PMID 27533466, 2016). "Although not specifically addressed in the present study, MYB overexpression does not seem to be limited to ACC but may occasionally occur also in other salivary gland tumors, such as acinic cell carcinoma, and basal cell and myoepithelial neoplasms." (PMID 35954356, 2022). "It is also possible that a number of cases which do not demonstrate aberrant expression of MYB or MYBL1 may represent other types of salivary gland tumors with an ACC-like morphology, such as polymorphous low-grade adenocarcinoma (PLGA) or basal cell adenocarcinoma." (PMID 27533466, 2016).
chronic myeloid leukemia (8 papers, 2013 to 2022). "Aberrant (enhanced) c-MYB expression has been found in various human malignancies including T-cell leukemia and acute and chronic myeloid leukemias." (PMID 26937281, 2016). "In addition, it was reported that c-MYB is a crucial transcriptional regulator that modulates the expression of ESPL1 in chronic myeloid leukemia." (PMID 35814478, 2022). "MiR-150 has been reported to be overexpressed in CLL and underexpressed in chronic myelogenous leukaemia (CML), where its decreased levels are suggested to potentiate MYB and BCR-ABL expression." (PMID 34968247, 2021). "In chronic myeloid leukemia (CML), miR-150 can target MYB and inhibit the expression of a series of oncogenes, thus suppressing the proliferation of CML cells." (PMID 34876130, 2021).
low grade glioma (8 papers, 2017 to 2025). A grade I or grade II glioma arising from the central nervous system. "In addition, 2% (2/131) of the cases were classified as other tumor types than diffuse glioma, i.e., low-grade glioma MYB/MYBL1 and (anaplastic) pleomorphic xanthoastrocytoma." (PMID 33941250, 2021).
neuroepithelial tumor (8 papers, 2017 to 2025). "However, shared mutations of MYB/MYBL1 abnormalities can occur in other low-grade neuroepithelial tumors, including DA (26–41%), d-OT (8%), IDG (77%), MYBL1 (54%), MYB (23%), and DNET (in one case)." (PMID 36699536, 2022).
thalassemia (8 papers, 2013 to 2026). An inherited blood disorder characterized by a decreased synthesis of one of the polypeptide chains that form hemoglobin. "Recently, a designed targeted gene panel, which included all eight globin genes and validated modulators (KLF1, BCL11A, and MYB), was applied in molecular screening and clinical genotyping in thalassemia." (PMID 30809867, 2019).
anemia (6 papers, 2013 to 2023). A reduction in the number of red blood cells, the amount of hemoglobin, and/or the volume of packed red blood cells. "Myb (MYB Proto-Oncogene, transcription factor) KO disrupts late-EMP and HSC differentiation (wave 2 and wave 3) and results in anemia and embryonic lethality around E15.5." (PMID 33681211, 2021).
cylindroma (6 papers, 2016 to 2022). "The finding of MYB activation in these inherited tumours is intriguing, since the underlying mechanism behind formation of inherited cylindromas has been shown to be largely limited to a germline mutation of CYLD and loss of heterozygosity at the CYLD locus." (PMID 26969893, 2016). "Here, we investigated inherited cylindromas from several families with germline CYLD mutations for the presence of MYB activation." (PMID 26969893, 2016). "Moreover, a considerable overexpression of MYB was observed in the CYLD‐defective cylindroma cells, while the knockdown of MYB expression caused a significant reduction in the proliferation of these cells." (PMID 32783365, 2020). "However, it remains to be determined whether MYB–NFIB fusion‐positive sporadic dermal cylindromas also carry bi‐allelic CYLD mutations, as these two changes could potentially act synergistically in promoting cylindroma development." (PMID 26969893, 2016). "Overexpression of MYB was, however, confirmed in cylindroma and spiradenoma cases using immunohistochemistry, suggesting that other mechanisms of gene overexpression are operative." (PMID 31101826, 2019). "Taken together with the recent findings of upregulated MYB in CCS tumors, this supports MYB as a key downstream mediator of cylindroma pathogenesis following loss of CYLD18." (PMID 31624251, 2019). "To further examine the role of MYB overexpression in the molecular pathogenesis of inherited cylindromas, we silenced the expression of MYB in CYLD‐defective cylindroma cells, using RNA interference." (PMID 26969893, 2016). "Taken together, our findings suggest molecular heterogeneity in the pathogenesis of sporadic and inherited cutaneous cylindromas, with convergence on MYB activation." (PMID 26969893, 2016). "To investigate the biological significance of MYB overexpression in cylindroma, given the lack of MYB–NFIB fusion transcripts, we used siRNAs to knock down MYB mRNA expression in cultured primary CYLD‐defective cylindroma cells." (PMID 26969893, 2016). "MYB protein expression in cylindromas and spiradenomas demonstrated nuclear localization (white arrows in inset) and increased intensity of staining when compared to perilesional tissues." (PMID 26969893, 2016). "Knock‐down of MYB mRNA and protein levels led to a significant decrease in cell proliferation of cylindroma cells in three independent experiments." (PMID 26969893, 2016). "We have previously shown that sporadic cylindromas express either MYB–NFIB fusion transcripts or show evidence of MYB activation in the absence of such fusions." (PMID 26969893, 2016). "Cylindromas are characterized by mutations in CYLD and approximately two- thirds of sporadic cylindromas have also been reported to carry the MYB-NFIB fusion gene, which leads to overexpression of MYB, analogous to adenoid cystic carcinoma." (PMID 31101826, 2019). "Notably, siRNA knock‐down of MYB in cylindroma cells resulted in down‐regulation of both BCL2 and BIRC3 mRNA levels." (PMID 26969893, 2016). "The occurrence of MYB–NFIB fusion transcripts in sporadic cylindromas and their absence in inherited cases may reflect the timing of a gained MYB activation state." (PMID 26969893, 2016). "It is also intriguing that MYB–NFIB fusions are seen in ACCs of the breast and salivary glands as well as in sporadic cylindromas, suggesting that MYB activation may be central to the histological patterning of these tumours." (PMID 26969893, 2016). "Moreover, knock‐down of MYB expression caused a significant reduction in cylindroma cell proliferation, suggesting that MYB is also a key player and oncogenic driver in inherited cylindromas." (PMID 26969893, 2016). "Our findings highlight that different tumourigenic events may ultimately converge on MYB, and that this oncoprotein represents a putative therapeutic target in sporadic and inherited cylindromas as well as in ACC." (PMID 26969893, 2016).
cylindroma (continued). "Notably, we also show that MYB drives the proliferation of CYLD‐defective cylindroma cells." (PMID 26969893, 2016). "We chose to explore the presence of MYB–NFIB fusion transcripts in tumours from patients with germline CYLD mutations, to determine whether such fusions were present at a similar frequency to that seen in sporadic cylindroma and ACC, which share histological similarities." (PMID 26969893, 2016). "Here, we demonstrate that MYB activation is also frequently seen in inherited cylindromas, but strikingly there was a lack of MYB–NFIB fusion transcripts in the 23 tumour samples studied." (PMID 26969893, 2016). "In line with this reasoning, it will be interesting to study whether NF‐κB inhibitors can down‐regulate MYB and inhibit the proliferation of CYLD‐defective cylindroma cells." (PMID 26969893, 2016). "We found that inherited cylindromas do not harbour MYB–NFIB gene fusions but instead show frequent overexpression of MYB mRNA and protein." (PMID 26969893, 2016). "Some genes, such as CD34, that have been described as MYB target genes in ACC 4 were, however, found to be underexpressed in cylindroma (fold change decrease = ×0.47), whilst genes such as MAD1L1 were not differentially expressed between tumours and controls (data not shown)." (PMID 26969893, 2016). "MYB is an attractive therapeutic target in ACC and treatments that are developed for ACC may hence be of relevance for patients with both sporadic and inherited cylindromas, and vice versa." (PMID 26969893, 2016). "This resulted in a significant inhibition of MYB target genes and proliferation of cylindroma cells from three independent tumours, suggesting that MYB activation drives the growth of CYLD‐defective cylindromas and potentially also the growth of MYB–NFIB‐positive sporadic cylindromas." (PMID 26969893, 2016). "Similar MYB staining patterns were seen in MYB–NFIB fusion‐positive and ‐negative sporadic cylindromas." (PMID 26969893, 2016). "The MYB-NFIB fusion was also absent from the spiradenomas and cylindroma–spiradenoma hybrid tumor." (PMID 31101826, 2019).
fungal infection (6 papers, 2020 to 2025). "Recent studies have emphasized the significance of ERF and MYB families in regulating responses to biotic stress with particular referment to B. cinerea and fungal infection, including the regulation of defense genes via JA/ET pathways." (PMID 39997418, 2025). "Among the most important transcription factors in plants, the v-myb avian myeloblastosis viral oncogene homolog (MYB) regulates the expression network of response genes under stresses such as fungal infection." (PMID 37089647, 2023). "Expression of the MYB, bHLH, C2H2-ZF, C2C2, WRKY, and NAC families was most differentially regulated upon fungal infections in tea." (PMID 37821523, 2023). "Furthermore, distinct TFs specifically regulate host gene expression under various biotic stressors, with MYB/NAC proteins mainly for bacterial infections and GATA and ERF factors for virus/virus and fungal infections, respectively." (PMID 39524930, 2024).
osteosarcoma (6 papers, 2022 to 2025). A usually aggressive malignant bone-forming mesenchymal neoplasm, predominantly affecting adolescents and young adults. "High levels of MYB in osteosarcoma (OS) are correlated with poor prognosis and resistance, and MYB-knockout in OS cells provoked a sensitization to treatment with doxorubicin and the antimetabolite methotrexate." (PMID 38835346, 2024).
B cell lymphoma (5 papers, 2017 to 2025). "Consistent with previous studies, in B-cell lymphoma, MSI2 binds to canonical targets such as MYB and IKZF2, and Ro treatment resulted in their loss of protein abundance." (PMID 36167829, 2022). "Likewise, MYB showed high expression in canine primary B-cell lymphoma samples." (PMID 36230614, 2022). "We observed increasing tumor clonality during progression of B-cell lymphomas and identified gene players (especially TERT and MYB) and biological processes involved in tumor progression." (PMID 29099869, 2017).
bladder cancer (5 papers, 2021 to 2025). "Interestingly, clusters with elevated MYB expression exhibited significant enrichment for disease-associated pathways such as bladder cancer and primary immunodeficiency." (PMID 40950184, 2025). "Further experiments confirmed that overexpression of MYB enhanced the ability of migration in bladder cancer." (PMID 36994664, 2023). "The results indicated a higher expression level of MYB in two bladder cancer cell lines, T24 and UM-UC3, compared with that in the normal urothelial cell line, SV-HUC-1." (PMID 36994664, 2023). "In the present study, we validated that MYB is up-regulated in bladder cancer and overexpression of MYB significantly reinforced the cell migration ability of bladder cancer cells." (PMID 36994664, 2023). "We confirmed that the expression level of MYB is significantly higher in bladder cancer cell lines than in urothelial cells through qRT-PCR." (PMID 36994664, 2023). "Quantitative real-time PCR (qRT-PCR) was conducted to verify the expression level of MYB in bladder cancer cell lines." (PMID 36994664, 2023). "Further experiments validated that overexpression of MYB enhanced the ability of migration in bladder cancer via wound healing assay and transwell assay." (PMID 36994664, 2023). "We first explored the effect of MYB in bladder cancer via basic experiments and validated that MYB is up-regulated in bladder cancer and overexpression of MYB significantly reinforced the cell migration ability of bladder cancer cells." (PMID 36994664, 2023). "Next, we suspected whether MYB played an oncogenic role in the progression of bladder cancer." (PMID 36994664, 2023).
liver cancer (5 papers, 2013 to 2025). An epithelial or non-epithelial malignant neoplasm that arises from the liver. "MYB- and HIF1α-co-regulated direct target, KRT19, exhibits positive correlation with HIF1α under hypoxia, while another target, ALDOA is shown to support hypoxic survival of liver cancer cells." (PMID 40680814, 2025). "Thus, miR-221 was suggested to negatively control MYBL1 in liver cancer, based on the miR-221-dependent downregulation of relative luciferase activity by the MYBL1 3′UTR27, and RNA-seq analysis in MCF-7 cells also indicated downregulation of MYB and MYBL1 by miR-221/22246." (PMID 30833639, 2019).